MYC (MYC proto-oncogene, bHLH transcription factor)
Diseases named in the same sentence as MYC in open-access papers (continued):
Sharing a sentence is not in itself a finding about the gene and the disease.
melanoma (continued). "FAO genes (MYC, MITF, and CTNNB1) were enriched in the MYC+ cell cluster, and overexpression of MITF was associated with greater LN metastasis in mouse footpad melanoma." (PMID 39858514, 2025). "The results demonstrate that human DANCR is a MITF and c-MYC regulated lncRNA oncogene that promotes melanoma cell proliferation and migration and that melanoma patients with high DANCR expression have significantly decreased survival rates." (PMID 41336739, 2025). "Arm-level gene alterations in chromosome 8q21-24, where RAD21, NBN, and MYC are located, were found in approximately one fourth of mucosal melanomas." (PMID 39823560, 2025). "For example, recent evidence suggests that lymph node metastasis require a metabolic shift towards FAO mediated by MITF, a transcription factor, in MYC+ melanoma." (PMID 40376583, 2025). "Lastly, the well-established oncogenes KRAS and MYC were also identified within melanoma-derived EV, supporting a potential role for EV-mediated transfer of these tumorigenic factors in promoting malignant transformation and tumor progression." (PMID 40805206, 2025). "Surprisingly, we find that primary adult melanocytes in healthy skin can also express the dedifferentiation program, but that spontaneous fluctuations of state, as well as the MYC program, appear to be exclusive to melanoma cells." (PMID 41405996, 2025). "For example, there is a subgroup of melanomas with increased chromosomal copy number gains in 8q24 at MYC, which is characterized by amelanotic appearance." (PMID 39519055, 2024). "Pathway analysis revealed that EGR3HI patients in melanoma exhibited reduced proliferation signals, such as MYC." (PMID 38973154, 2024). "Mining of a SOX10 KD dataset identified MITF, SCD, and MYC as being downstream SOX10 effector genes in this melanoma phenotype." (PMID 38994683, 2024). "The different response rates to BRAF V600E‐targeted drugs between BRAF V600E‐mutated melanoma and CRC, and the differential expression pattern of HSPA8 and MYC were consistent with our findings." (PMID 37973552, 2024). "It has been previously identified that most of these pathways converge to activation of oncogenic c-MYC to confer both inherent and acquired resistance against targeted therapy like BRAFi in mutant melanoma." (PMID 39238805, 2024). "Other transcriptional factors involved in PD-L1 regulation in melanoma include MYC, hypoxia-inducible factor-1α and 2α (HIF-1α/2α), STAT3 and NF-κB." (PMID 38633217, 2024). "MYC amplification and PTEN loss were mostly prevalent in breast tumors, while amplifications for SOX2 were mostly observed in melanoma." (PMID 38398121, 2024). "Subsequently, these sets were modified to 9p21 (CDKN2A), 6p25 (RREB1), 11q13 (CCND1), and 8q24 (MYC), improving the discriminatory power in differentiating melanomas from nevi." (PMID 38247727, 2024). "Of note, treatment of Nrf2 depleted cells with BRAF or MYC inhibitor results in a higher survival rate of melanoma cells." (PMID 36747120, 2023). "For instance, CX-5461 is utilized for the treatment of BRCA1/2 deficient tumors through topoisomerase II inhibition, and melanoma cell lines have been treated with G4 ligand RHPS4 that targets the MYC gene among others." (PMID 36980918, 2023). "The expression of these genes was also positively correlated with that of MYCN in the melanomas but inversely correlated with that of MYC." (PMID 36768931, 2023). "The MYC+ Melanoma (MYC+MEL) and FGFBP2+NKT subclusters are tightly correlated with LN metastasis and poor prognosis." (PMID 38065972, 2023). "Significantly weaker expression of the JARID1B, E2F1 and c-MYC genes was clearly seen in melanoma cells that overexpressed Pirin relative to the control cells." (PMID 37308689, 2023). "Other approaches for MYC inhibition have been carried out using nanoparticles with anisamide-targeted MYC-specific siRNA to enter melanoma cells upon binding to a cell-specific sigma receptor using murine and human xenograft tumor models." (PMID 36969025, 2023).
melanoma (continued). "A cellular myelocytomatosis viral oncogene (c-MYC) binding site within the Noxa promoter has been identified, and siRNA knockdown of c-MYC reduced bortezomib-induced Noxa mRNA expression in multiple melanoma cell lines, MDA-MB-231 cells, and HeLa cells." (PMID 35207544, 2022). "For example, knocking down PP2A or PP2A inhibition by okadaic acid (OA) contributes to c-MYC stabilization, aberrant proliferation, and increased sensitivity to paclitaxel, doxorubicin and temozolomide in melanoma cells." (PMID 36358647, 2022). "On the other hand, PPP2R5A downregulation contributes to increased c-MYC-induced senescence in melanomas." (PMID 36358647, 2022). "To further confirm the effect of RAI14 knockdown on the expression of c-MYC in melanoma cells, we performed the Western blot and qPCR assays." (PMID 36233342, 2022). "High MYC expression in BRAF‐mutant melanomas that progressed after BRAF inhibitor therapy was identified as the common denominator between diverse resistance pathways (ERK, PI3K, etc.)." (PMID 36214609, 2022). "The protein level of c-MYC is upregulated in melanoma cells, and numerous cellular processes are regulated by c-MYC, including cell proliferation, migration, and invasion." (PMID 36233342, 2022). "MYC, known as an important oncogenic regulator, has a high fraction of amplification events in melanoma samples, contributing to the overactivation of the MYC oncogenic pathway." (PMID 34122516, 2021). "Our study highlighted the significance of MYC in melanoma progression from both tumor-intrinsic and -extrinsic perspectives." (PMID 34122516, 2021). "Inhibiting MYC in melanoma will bring a reduction in tumor proliferation and potentially remodel the tumor microenvironment into immune hot, leading to the increased sensitivity of immunotherapy." (PMID 34122516, 2021). "Overexpressing c-MYC promotes melanoma metastasis and is obviously related with distant metastasis and poor prognosis." (PMID 34116677, 2021). "For patient CAS-D, the prediction of ploidy differences between spatially distinct cores of the primary melanoma was supported by FISH to MYC and the chromosome 8 centromere." (PMID 33664264, 2021). "Aberrant MYC (gain) and CDKN2A (loss or mutation) have been frequently detected in various human cancers, including melanoma." (PMID 34885165, 2021). "Recently, 2-[[(5-bromo-2-thienyl)methylene]amino]-benzamide (BTYNB) was identified as a selective inhibitor of CRD-BP binding to the CRD region of MYC mRNA thereby increasing MYC turnover in melanoma and ovarian cancer cells." (PMID 33176745, 2020). "The deletion of the MYC gene in macrophages results in a reduced expression of these factors, a defective tumor angiogenesis and a reduced tumor growth in mouse melanoma and fibrosarcoma models." (PMID 32523087, 2020). "Of note, we found MYC amplifications in each of the eight uveal melanoma patients, which is a significant difference to the other melanoma subtypes (p < 0.05)." (PMID 32825510, 2020). "In particular, diclofenac induces apoptosis, associated with mitochondrial dysfunction, and restrains both glucose metabolism and MYC expression in melanoma." (PMID 32528879, 2020). "ERK activation results in phosphorylation (pFRA1) and induction of the transcription factors, FRA1/FOSL1 and MYC, which are critical for melanoma development, progression, and resistance." (PMID 33122628, 2020). "BRD4 depletion in A375 melanoma cells using the CRISPR/Cas9 system significantly decreased the expression of c-MYC and suppressed the ability of these cells to form colonies." (PMID 32286255, 2020). "In accordance, c-MYC has previously been implicated in suppression of BRAFV600E-induced senescence in melanocytes and melanoma progression, while loss of CDK7 results in senescence." (PMID 30651597, 2019).
melanoma (continued). "Accordingly, MG132 treatment of melanoma cells caused an accumulation of CDK7 and rescued its expression under experimental depletion of MITF or c-MYC, the latter of which is an established target of several ubiquitin ligases." (PMID 30651597, 2019). "The systems biology analysis performed in this study revealed that upregulation of self-renewing genes in CD271+ melanoma cells occurs in response to the activation of E2F, MYC, and SREBF1 promoter-containing elements." (PMID 31118427, 2019). "Nevertheless, transcriptional re-wiring of c-MYC has recently been described in BRAF-inhibitor resistant melanoma sensitizing to bromodomain inhibition." (PMID 30651597, 2019). "The dependence of TFIIH-CAK on the sequence-specific transcriptional master regulators MITF or MYC constitutes a vulnerability in melanoma." (PMID 30651597, 2019). "The concordant expression of MITF and c-MYC transcripts was confirmed in a panel of genetically heterogeneous melanoma lines by RT-PCR." (PMID 30651597, 2019). "In detail, activated RAS signaling through effector ERK resulted in phosphorylation and stabilization of c-MYC by attenuation of its ubiquitin-mediated protein degradation mechanism in melanoma." (PMID 30001368, 2018). "Since in our model SIRT1 represses Mxd1 gene expression, we suggest that MYC is activated in melanoma progression." (PMID 29383100, 2017). "SIRT1 promoted Mxd1 silencing, which led to increased activity of MYC oncogene contributing to melanoma progression." (PMID 29383100, 2017). "In melanoma, MYC directly regulates genes in melanocytes, and targeting these nucleotide pools has an effect similar to reduction in MYC protein expression." (PMID 28362357, 2017). "Of note, MYC upregulation has different effects on the spliceosome in different tumour types and it remains to be seen if this effect carries over into melanoma." (PMID 28097822, 2017). "For the first time, we show an interaction between SIRT1 and MYC/MAX/MAD network in melanoma progression, highlighting the SIRT1 role in the regulation of important pathways related to cancer." (PMID 29383100, 2017). "WP1130 (degrasyn, (2E)-3-(6-bromo-2-pyridinyl)-2-cyano-N-[1S-phenylbutyl]-2-propenamide) is a partially selective DUB inhibitor initially identified as a stabilizer of Bcr/Abl in chronic myelogenous leukemia and a negative regulator of MYC in melanoma." (PMID 29134486, 2017). "MYC is a proto‐oncogene and transcription factor that is amplified or overexpressed in around 6% of melanomas." (PMID 28097822, 2017). "In the present study, we demonstrated successful reprogramming of terminally differentiated melanoma TILs that express high levels of PD-1 into human iPSCs by using SeV vectors encoding OCT3/4, SOX2, KLF4, and c-MYC." (PMID 27057178, 2016). "Promoter-based analyses and further validation in tissue specimens revealed the neural crest lineage master regulator SOX10 and the oncogene MYC as new upstream drivers of RAB7 transcription in melanomas." (PMID 26008978, 2015). "Consistent with this scenario, inactivation of the RAB7 transactivator MYC in melanoma cells can re-activate dormant senescence programs reminiscent of OIS in melanocytes." (PMID 26008978, 2015). "Compounds selected in the present study differentially altered the expression of melanocyte/melanoma specific microphthalmia-associated transcription factor (MITF) and proto-oncogene c-MYC." (PMID 24595456, 2014). "c-MYC inhibition in melanoma cells results in reduced proliferation through mechanisms involving several enzymes of nucleotide biosynthesis." (PMID 24595456, 2014). "In human melanoma cells, a decrease in c-MYC expression has been reported to enhance the effect of IR and cisplatin treatment." (PMID 19134217, 2009).
melanoma (continued). "Here, we isolate distinct melanoma states with unique phenotypes: a MYC-driven state, essential for tumor initiation yet sensitive to BRAF inhibition, and a dedifferentiated, invasive BRN2-high state enriched in therapy-resistant cells but not directly tumorigenic." (PMID 41405996, 2025). "Taken together, these observations suggest that NOLC1 is a transcriptional target co-regulated by the CoREST complex and MYC, and that its overexpression may play a significant role in melanoma progression." (PMID 41227344, 2025). "We computed Pearson correlations between the DEDIFF and MYC programs for each melanoma cell line." (PMID 41405996, 2025). "To explore the possibility of the CoREST complex and MYC cooperatively playing a regulatory role in the transcriptional activation of RNA processing genes, we performed RCOR1 and MYC chromatin immunoprecipitation sequencing (ChIP-seq) for both RCOR1 and MYC in A375 melanoma cells." (PMID 41227344, 2025). "TWIST1 and MYC demonstrated substantial expression in C3 HHATL+ melanoma cells." (PMID 41383633, 2025). "PHF10 could also interact with MYC and facilitate the recruitment of PBAF complex to target gene promoters, therefore, amplifying MYC transcriptional activation of genes involved in the cell cycle progression of melanoma cells." (PMID 39904827, 2025). "Mechanistically, c-MYC has been reported to mediate PI induction of NOXA in melanoma cells, whereas NOXA transcription can also be regulated by ATF3/ATF4 in the non-PI setting through a variety of signaling pathways, including the endoplasmic reticulum stress pathway." (PMID 39302104, 2024). "In contrast, immune exclusion genes, e.g., MYC, demonstrated an upregulation in PD1res melanomas." (PMID 38594286, 2024). "In addition to the role of BRAF, the role of c‐MYC in the regulation of senescence in melanoma is also important." (PMID 39161800, 2024). "Intriguingly, these genes that were downregulated in response to the RC48 and dabrafenib treatment, and were also observed to be overexpressed and associated with poor prognosis in melanoma TCGA cohort, were also components of the most enriched pathways identified by GSEA (E2F and MYC)." (PMID 38594618, 2024). "Notably, GSEA revealed the involvement of several pathways, including G2M checkpoint, E2F targets, mitotic spindle, DNA repair, spermatogenesis, and MYC targets, which are highly relevant to tumor progression, including melanoma." (PMID 39052109, 2024). "Hence, the adaptation of a five-probe FISH assay targeting against 9p21 (CDKN2A), 11q13 (CCND1), and 8q24 (MYC) has improved the discriminatory power for spitzoid melanomas." (PMID 38247727, 2024). "We also considered the alternate hypothesis that the effects of MYCN or MYC expression on survival results from their expression in melanoma cells." (PMID 36768931, 2023). "Because MYC reportedly induces IMPDH2 in melanoma, we used a specific inhibitor of MYC (10058-F4)." (PMID 37409959, 2023). "Additionally, our findings are consistent with previous reports in which cryptolepine reduced c-MYC levels in melanoma cells." (PMID 37513937, 2023). "Taken together, these findings suggest that the combination of ICIs with a form of MYC inhibition could be a potential therapeutic avenue in ICI-refractory melanoma." (PMID 36977461, 2023). "Notably, these phenotypes appeared independent of changes in MYC protein expression, an established downstream target of IRF4, suggesting MYC‐independent or a pleiotropic role for IRF4 in melanoma cell survival." (PMID 36219477, 2023). "We also found that overexpression of RAI14 in melanoma cells reduced the turnover rate of c-MYC." (PMID 36233342, 2022). "In addition to CD68 and CD163 markers, it has also been described that MYC controls the expression of M2 specific genes, and its depletion in MYC+ macrophages inhibited tumor growth in melanoma and fibrosarcoma mouse models." (PMID 35326620, 2022).
melanoma (continued). "Taken together, these data may suggest that RAI14 regulates melanoma progression by affecting c-MYC expression." (PMID 36233342, 2022). "Moreover, melanoma cells display high activity of the transcription factor MYC, a master regulator of cell metabolism that operates as a well-known oncogene in melanoma and other cancer types." (PMID 35912100, 2022). "Most importantly, while MYC overexpression induced resistance to BRAF inhibitors in melanoma cells in vitro, it also sensitized the cells to inhibitors of glucose metabolism, glutaminolysis and other metabolic processes, pointing to actionable MYC‐induced metabolic dependencies." (PMID 36214609, 2022). "Furthermore, transwell assay results indicated that overexpression of c-MYC restored cell migration ability of melanoma of the RAI14 knockdown group." (PMID 36233342, 2022). "There is also a rationale for the role of MYC in melanoma resistance to BRAF/MEK inhibitors." (PMID 35565444, 2022). "Interestingly, CIP2A-mediated PP2A inhibition or pharmacological inhibition of PP2A using okadaic acid (OA) increases c-MYC levels and contributes to sensitivity to chemotherapies such as paclitaxel, doxorubicin and temozolomide in melanoma cells." (PMID 36358647, 2022). "Treatment of RAI14 knockdown melanoma cells with MG132 partly rescued c-MYC protein expression." (PMID 36233342, 2022). "In this study, we found that RAI14 can affect the expression of c-MYC in melanoma cells." (PMID 36233342, 2022). "Interestingly, the expression of RAI14 was found to correlate with c-MYC signaling in melanoma by analyzing the R2 database." (PMID 36233342, 2022). "Additionally, high c-MYC expression in mucocutaneus melanoma correlates with immune evasion and tumor invasiveness, hence, its association with poor prognosis and survival." (PMID 35048028, 2021). "As a result, high MYC activity induces melanoma tumor growth, further leading to metastasis." (PMID 34122516, 2021). "Canonical miR-27b-3p inhibits the development of melanoma by targeting MYC." (PMID 34698264, 2021). "IRE1α-XBP1s promoted melanoma cell proliferation by directly regulating IL-6 transcription 12.XBP1s could directly activate c-MYC expression." (PMID 32489465, 2020). "In conclusion, our research unveiled that circ-GLI1 interacted with p70S6K2 to boost GLI1 and β-catenin proteins, so as to activate Hedgehog/GLI1 and Wnt/β-catenin pathways and therefore enhance MYC-activated Cyr61 expression, leading to accelerated metastasis in melanoma." (PMID 32732916, 2020). "Nevertheless, patients with anorectal melanoma, liver metastases or melanoma with amplified MYC seem to have an increased risk of not benefitting from ICI." (PMID 32110946, 2020). "Expectedly, Cyr61 expression was decreased along with MYC downregulation in melanoma cells." (PMID 32732916, 2020). "In addition, we illustrated that circ-GLI1 activated Hedgehog/GLI1 and Wnt/β-catenin pathways to induce MYC-regulated transactivation of Cyr61 in melanoma." (PMID 32732916, 2020). "In particular, at early stages of melanoma development, Rab7a is upregulated and sustains melanoma cell proliferation controlled by the lineage-specific transcription factor SOX10 and the oncogenic transcription factor MYC, which is activated at early stages of melanoma development." (PMID 33195279, 2020). "Thus, significant pathway enrichment connected CD271 in melanoma with gene targets of E2F, MYC, SREBP1, and PI3-kinase signaling." (PMID 31118427, 2019). "Given c-MYC’s major role in transcript maturation, its central position as a molecular driver in melanoma development, and the ability to confer resistance to chemotherapy, we herein examined the transcriptional expression profile of c-MYC gene in BCC, SCC, and melanoma biopsy specimens." (PMID 30795533, 2019).